LINC01711 (long independently transcribed non-coding RNA 1711)
Synonyms: MGC4294
Gene: Long non-coding RNA gene on chromosome 20 (58,634,772 to 58,635,738, forward strand). Ensembl gene ENSG00000268941.
Diseases named in the same sentence as LINC01711 in open-access papers:
LINC01711 is named in the same sentence as 10 diseases in open-access papers, as found by Europe PMC text mining. Sharing a sentence is not in itself a finding about the gene and the disease. The quoted sentences say what the papers report.
bladder cancer (2 papers, 2022 to 2023). "Elevated LINC01711 expression in bladder cancer was found to be associated with decreased survival." (PMID 36105083, 2022). "Elevated expression of LINC01711 in bladder cancer correlates with reduced survival." (PMID 36874011, 2023).
esophageal squamous cell carcinoma (2 papers, 2021 to 2023). Esophageal squamous cell carcinoma (ESCC) is a type of esophageal carcinoma (EC) that can affect any part of the esophagus, but is usually located in the upper or middle third. "Through its interaction with miR-326 and FSCN1, LINC01711 has been shown to promote esophageal squamous cell carcinoma initiation and progression." (PMID 36874011, 2023). "LINC01711 also have prognostic ability in esophageal squamous cell carcinoma." (PMID 34408984, 2021).
esophageal cancer (1 paper, 2023). A primary or metastatic malignant neoplasm involving the esophagus. "LINC01711 is markedly expressed in esophageal cancer and has been linked to substandard prognosis by promoting tumor cells proliferation, migration, and invasion properties through FSCN1 upregulation and miR-326 downregulation." (PMID 38071230, 2023).
lung carcinoma (1 paper, 2025). "Expression of LINC01711 rose in lung cancer cell lines including PC9, H1299, and H1975 but fell in A549.GSEC showed no significant changes in expression in these cancer cell lines." (PMID 39995658, 2025).
cancer (5 papers, 2021 to 2025). A tumor composed of atypical neoplastic, often pleomorphic cells that invade other tissues. "The results revealed a significant overlap between LINC01711 and FAP expression, indicating that LINC01711 is predominantly expressed in FAP-positive cancer-associated fibroblasts (CAFs)." (PMID 40855046, 2025). "Among these pathways, we found that LINC01711 was involved in the regulation of actin and pathways in cancer, suggesting that LINC01711 may regulate the migration or invasion of tumor cells." (PMID 34370713, 2021). "The results displayed that the top five lncRNAs were AC107464.3, LINC01711, LINC00862, LINC00324, and AC009120.2; they affected 17, 16, 14, 14, and 12 cancer types, respectively." (PMID 36874011, 2023).
tumor (5 papers, 2021 to 2025). "We have shown that TGF-β induces LINC01711 expression in glioma cells and that the levels of LINC01711 are elevated in GBM tumour samples, and its expression is associated with poor patients’ survival and prognosis." (PMID 37891744, 2023). "The result showed that LINC01711 is upregulated in tumor tissue and is specifically overexpressed in FAP+ CAFs." (PMID 40855046, 2025). "Through siRNA knockdown, we confirmed that the pro-tumor effect of LINC01711 was mediated through modulating FSCN1 expression." (PMID 34370713, 2021). "To test whether LINC01711 level affects tumor growth in vivo, we transplanted TE-1 cells in nude mice." (PMID 34370713, 2021). "Similarly, we found that downregulation of LINC01711 inhibited tumor growth in mice." (PMID 34370713, 2021). "LINC01711 knockdown results in downregulating ZEB1, a crucial transcription factor that promotes tumour cell invasion and EMT." (PMID 37891744, 2023).
LINC01711 also shares sentences with these, for which no sentence is quoted: fibrosis (1 paper); glioblastoma multiforme (1); Hepatic fibrosis (1); renal carcinoma (1).